MXD3 (MAX dimerization protein 3)
Description:
Transcriptional repressor. Binds with MAX to form a sequence-specific DNA-binding protein complex which recognizes the core sequence 5'-CAC[GA]TG-3'. Antagonizes MYC transcriptional activity by competing for MAX and suppresses MYC dependent cell transformation (By similarity).
Synonyms: bHLHc13; MAD3; MYX
Tractability: PROTAC: ubiquitination databases record sites on it.
Gene: Protein-coding gene on chromosome 5 (177,301,461 to 177,312,757, reverse strand). Ensembl gene ENSG00000213347.
Subcellular location: Nucleus
Subcellular location (Human Protein Atlas): Nucleoli; Nucleoplasm
Gene Ontology:
Molecular function: protein binding; DNA-binding transcription factor activity, RNA polymerase II-specific; RNA polymerase II cis-regulatory region sequence-specific DNA binding; DNA binding; DNA-binding transcription repressor activity, RNA polymerase II-specific; protein dimerization activity; RNA polymerase II transcription regulatory region sequence-specific DNA binding
Biological process: regulation of transcription by RNA polymerase II; negative regulation of transcription by RNA polymerase II
Cellular component: chromatin; nucleus; RNA polymerase II transcription regulator complex
Genetic constraint (gnomAD): Loss-of-function variants: 20 observed, 24.76 expected, observed/expected ratio (o/e) 0.81, 90% interval 0.57 to 1.17. The synonymous counts are far from expectation, so gnomAD's model fits this gene poorly and the ratio says little. Missense variants: 298 observed, 260.27 expected, observed/expected ratio (o/e) 1.14, 90% interval 1.04 to 1.26. Synonymous variants: 150 observed, 118.66 expected, observed/expected ratio (o/e) 1.26, 90% interval 1.11 to 1.45.
Homologues: Orthologues: macaque MXD3 (99% identical), pig MXD3 (91% identical), guinea pig MXD3 (89% identical), dog MXD3 (87% identical), chimpanzee MXD3 (85% identical), mouse Mxd3 (84% identical), rat Mxd3 (74% identical), tropical clawed frog mxd3 (61% identical), zebrafish mxd3 (56% identical), Caenorhabditis elegans mdl-1 (33% identical). Paralogues in human: MXD4 (45% identical), MXD1 (44% identical), MXI1 (42% identical), MNT (31% identical).
Diseases named in the same sentence as MXD3 in open-access papers:
MXD3 is named in the same sentence as 56 diseases in open-access papers, as found by Europe PMC text mining. Sharing a sentence is not in itself a finding about the gene and the disease. The quoted sentences say what the papers report.
medulloblastoma (8 papers, 2012 to 2022). A malignant, invasive embryonal neoplasm arising from the cerebellum. "Our findings are consistent with previous clinical and preclinical studies, which demonstrated that MXD3 was highly expressed in neuroblastoma and medulloblastoma cells, and it was associated with high-risk features." (PMID 34584637, 2021). "MXD3 is highly expressed in neuroblastoma and medulloblastoma cell lines, and it was associated with high-risk features." (PMID 34584637, 2021). "Interestingly, we found that MXD3 is overexpressed in tumor tissue from the PTCH deficient heterozygote mouse model of medulloblastoma." (PMID 25053245, 2014). "Constant MXD3 overexpression, however, in mouse GNPs and human medulloblastoma cells, resulted in restrained cell proliferation as a result of the activated apoptosis." (PMID 34943942, 2021). "Previously, MXD3 overexpression was detected to elevate in glioblastoma, medulloblastoma, acute lymphoblastic leukemia cell proliferation, renal cell carcinoma, and hepatocellular carcinoma (HCC)." (PMID 34943942, 2021). "Evidence supports MXD3 in promotion of medulloblastoma and both LINC01089 and H1FX-AS1 display tumor suppressive functions." (PMID 33498739, 2021). "MXD3 has been shown to be overexpressed and to be required for medulloblastoma and acute lymphoblastic leukemia cell proliferation." (PMID 30838212, 2019). "In previous studies we demonstrated that knock-down of MXD3 in the human medulloblastoma cell line DAOY resulted in decreased proliferation." (PMID 25053245, 2014). "In this study, we use 4-OHT inducible human medulloblastoma cell lines to show that MXD3 activation results in a transient increase in cell proliferation." (PMID 25053245, 2014). "Persistent overexpression of MXD3, however, in mouse GNPs and in human medulloblastoma cells results in decreased proliferation due to the activation of apoptosis." (PMID 25053245, 2014). "The results presented in this report support the conclusion that MXD3 is required for proliferation of DAOY medulloblastoma cells; however, persistent and/or high expression of MXD3 ultimately leads to apoptosis and cell death." (PMID 22808009, 2012). "Database analysis suggests that MXD3 is overexpressed in human cancers, predominantly in medulloblastomas and glioblastomas." (PMID 22808009, 2012). "Based on ChIP-chip experiments, we present a list of candidate genes that seem to be directly bound by MXD3 to modulate transcription in DAOY medulloblastoma cells." (PMID 22808009, 2012). "Taken together, these results indicate that abnormally high MXD3 expression is a characteristic of at least a subset of medulloblastomas." (PMID 22808009, 2012). "Here, we present evidence that MXD3 promotes proliferation; however, sustained high levels of the protein negatively influence proliferation of medulloblastoma cells by the induction of programmed cell death." (PMID 22808009, 2012). "Moreover, recently we showed that MXD3 is upregulated in human medulloblastomas and is required for the proliferation of the human medulloblastoma cell line DAOY." (PMID 25053245, 2014). "Probing a small cohort of tumor samples by qRT-PCR validated the database analysis, supporting our initial hypothesis that MXD3 might be relevant to medulloblastoma proliferation." (PMID 22808009, 2012). "Mxd3 is upregulated in mouse models of medulloblastoma as well as in human medulloblastomas." (PMID 22808009, 2012). "MXD3’s dual effect on medulloblastoma cell proliferation may be another example of this increasingly complex regulation." (PMID 22808009, 2012). "Interestingly, 8 out of 10 human medulloblastoma samples analyzed showed MXD3 levels significantly higher than normal mature cerebellum (p<0.05)." (PMID 22808009, 2012). "Our results suggest that MXD3 is necessary for DAOY medulloblastoma cell proliferation." (PMID 22808009, 2012). "Taken together, these findings prompted us to explore the role of MXD3 in human medulloblastomas." (PMID 22808009, 2012).
medulloblastoma (continued). "The results presented thus far suggest a role for MXD3 in medulloblastoma proliferation." (PMID 22808009, 2012). "Finally, MXD3 appears to be expressed in human medulloblastomas, suggesting a role in medulloblastoma biogenesis, maintenance and/or proliferation." (PMID 22808009, 2012). "To test this hypothesis, we studied the role of MXD3 in medulloblastoma using the human medulloblastoma cell line DAOY." (PMID 22808009, 2012). "Therefore, we hypothesize that MXD3 plays a role in the cellular events that lead to medulloblastoma biogenesis." (PMID 22808009, 2012). "Furthermore, this might also reflect why MXD3 levels are so low in the medulloblastoma-derived DAOY cell line." (PMID 22808009, 2012). "Furthermore, MXD3 has been shown to be upregulated in proliferating cerebellar granule neuron precursors (GNPs), in cerebellar tumors derived from the patched heterozygous mouse model of medulloblastoma, in human medulloblastoma, and in human acute lymphoblastic leukemia (ALL)." (PMID 30838212, 2019). "Ptc+/− mice, a model for medulloblastoma, show high expression of MXD3 in the tumor tissue but not in the adjacent normal postmitotic cerebellar tissue." (PMID 22808009, 2012). "Indeed, analysis of expression databases suggested that MXD3 is expressed in many human neoplasias, and in particular in tumors of the CNS, most significantly in glioblastomas and medulloblastomas, while it is absent in most human adult tissues." (PMID 22808009, 2012). "Furthermore, MXD3 is expressed in tumors derived from patched heterozygous (ptc+/−) mice (a model for medulloblastoma,) but not in surrounding normal mature cerebellar tissue." (PMID 22808009, 2012). "Since MXD3 promotes GNP proliferation during normal cerebellar development and it is abnormally expressed in cerebellar tumors in ptc+/− mice, we reasoned that it might play an important role in the pathways that lead to uncontrolled proliferation in human medulloblastoma." (PMID 22808009, 2012).
glioma (7 papers, 2020 to 2025). A benign or malignant brain and spinal cord tumor that arises from glial cells (astrocytes, oligodendrocytes, ependymal cells). "MXD3 regulates critical cellular processes such as growth, differentiation, and apoptosis, and its dysregulation has been implicated in a range of cancers, including glioma and leukemia." (PMID 40406509, 2025). "We also found a higher expression of MXD3 and promoter according to the increasing glioma WHO grade or histologic types." (PMID 34859046, 2021). "For gliomas of primary origin, lower MXD3 promoter methylation indicated worse patient outcomes (p < 0.001)." (PMID 34859046, 2021). "Our study shows that MXD3, as a poor prognostic factor, plays a significant role in many cancers, especially glioma." (PMID 34859046, 2021). "To determine MXD3 expression in cancers, we chose glioma as the target cancer because its high expression in glioma implies meaningful poor survival in both TCGA and GEO datasets." (PMID 34859046, 2021). "The data from the CGGA on MXD3 in gliomas illustrate that MXD3 expression differs significantly in different grades of gliomas and glioma histologic grade." (PMID 34859046, 2021). "Xiaoyu Zhang and colleagues reported MXD3 played an important role in predict prognosis of glioma, and may expected to be as a clinical therapeutic target via analyzing public databases and experimental validation." (PMID 35586489, 2022). "Moreover, the MXD3 expression levels were correlated with overall survival in 3/4 of the glioma cohorts (Nutt_Glioma@PRECOG, TCGA, and GSE16011@PRECOG) and likewise with CTL levels in 3/4 of the glioma cohorts (ca00037@PRECOG, TCGA, and GSE16011@PRECOG)." (PMID 35879775, 2022). "Finally, we used IHC to verify the higher expression of MXD3 in glioma samples compared to normal samples." (PMID 34859046, 2021). "Similarly, there were significant differences in the promoter methylation of MXD3 among the different WHO glioma subtypes (p = 2e-6)." (PMID 34859046, 2021). "Glioma patients with high MXD3 or MXD3 promoter expression had poor survival." (PMID 34859046, 2021). "Briefly, the more malignant the glioma is, the higher the MXD3 expression is." (PMID 34859046, 2021). "Finally, we verified the high expression of MXD3 in gliomas by immunohistochemistry." (PMID 34859046, 2021). "The Max dimerization protein 3 (MXD3), member of MAD family, has been considered a potential target for therapeutic treatment of brain and central nervous system cancers due to its role in cellular proliferation and tumorigenesis." (PMID 32141244, 2020). "However, the difference in MXD3 promoter methylation across recurrent glioma patients was not significant (p = 0.99)." (PMID 34859046, 2021). "The expression of MXD3 protein in gliomas was significantly higher than that in normal samples." (PMID 34859046, 2021).
neuroblastoma (6 papers, 2021 to 2025). Neuroblastoma (NB) is the most common solid, extracranial childhood tumor. "Nanocomplexes made of superparamagnetic iron oxide NPs and an antisense oligonucleotide targeting the transcription regulator MAX dimerization protein 3 (MXD3, highly expressed in high-risk neuroblastoma) were developed to improve neuroblastoma treatment." (PMID 39125610, 2024). "MXD3 is a proliferation-promoting factor in neuroblastoma and B-cell lymphoma, which is consistent with our analysis." (PMID 34859046, 2021). "The nanocomplexes were tested in vitro in two human neuroblastoma cell lines, and immunofluorescence for MXD3 using Alexa® 488-labelled probes showed a drastic decrease in this factor in treated cells, while the apoptotic rate, evaluated using FITC-labelled annexin V and propidium iodide, increased." (PMID 39125610, 2024). "MXD3 has been shown to predict poor prognosis in clear cell renal cell carcinoma and hepatocellular carcinoma, as well as having been indicated as a new molecular targeted site to treat neuroblastoma." (PMID 35495629, 2022).
glioblastoma (5 papers, 2012 to 2022). The most malignant astrocytic tumor (WHO grade IV). "Here we leverage available TCGA datasets and examine both splice variants of MXD3 in human glioblastoma cells to investigate the role of MXD3 splicing." (PMID 30838212, 2019). "A previous study has also implicated MXD3 alternative splicing in glioblastoma multiforme (GBM)." (PMID 34584637, 2021). "Mxd3 is over-expressed in multiple cancers, including acute lymphocytic leukemia and glioblastoma and at least 17 different tumor types show survival differences that correlate with MXD3 expression levels." (PMID 35203395, 2022). "Our analysis revealed that the melanoma, glioblastoma, and kidney cancer cohorts with low MXD3 expression exhibited higher clinical benefits of ICB therapy (PD-1 or PD-L1)." (PMID 34584637, 2021). "Our analysis also revealed that glioblastoma, ovarian, and breast cancer patients with higher MXD3 expressions were resistant to chemotherapies." (PMID 34584637, 2021). "We found that glioblastoma, ovarian, and breast cancer patients with higher MXD3 expressions were resistant to chemotherapies, while colorectal cancer patients with higher MXD3 expression benefited more from chemotherapies than cohorts with lower expression." (PMID 34584637, 2021). "Within the glioblastoma samples, MXD3.E6 represents 58.87% of the measured total MXD3 population, while MXD3.E7 represents 43.94% of the measured total MXD3 transcript levels." (PMID 30838212, 2019). "Across the datasets, we find that MXD3 has the highest overexpression in glioblastoma with a fold change of 4.26 relative to normal tissues (p = 1.43E-08, Welch's t-test)." (PMID 30838212, 2019). "Furthermore, the anti-apoptotic function of MXD3 has been identified in glioblastoma and B-cell acute lymphoblastic leukemia." (PMID 34859046, 2021). "MXD3 is overexpressed in many types of cancers with glioblastoma being one of the highest." (PMID 30838212, 2019). "In addition, we found that lower expression levels of MXD3 were associated with clinical benefits of ICB therapy (PD-1 or PD-L1) in melanomas, glioblastomas, and kidney cancer and hence exhibited prolonged survival periods compared to cohorts with high MXD3 expression levels." (PMID 34584637, 2021). "However, overexpression of MXD3 was associated with shorter survival of prostate adenocarcinoma (PRAD), mesothelioma (MESO), LGG, KICH, uveal melanoma (UVM), lung adenocarcinoma (LUAD), KIRC, ACC, THYM, HNSC, LICH, and glioblastoma multiforme (GBM)." (PMID 34584637, 2021). "Specifically, we looked at MXD3 alternative splicing in glioblastoma multiforme (GBM) and find notable functional differences between the splice variants." (PMID 30838212, 2019). "Analysis of RNA-seq glioblastoma data available from TCGA reveals that MXD3 transcripts are significantly overexpressed relative to normal tissues." (PMID 30838212, 2019). "With currently available antibodies we were not able to visualize endogenous MXD3 in either U87-MG or T98G human glioblastoma cell lines (data not shown) although mRNAs are present." (PMID 30838212, 2019).
acute lymphoblastic leukemia (4 papers, 2019 to 2022). Leukemia with an acute onset, characterized by the presence of lymphoblasts in the bone marrow and the peripheral blood. "Besides, MXD3 was reported to be a potential therapeutic target in pre-B cell acute lymphoblastic leukemia." (PMID 36704352, 2022).
Obesity (4 papers, 2020 to 2025). Accumulation of substantial excess body fat. "The MXD3 gene is a transcription factor that has been previously reported to be associated with obesity, and it can promote the lipid‐related pathway, thereby impacting visceral adiposity." (PMID 41473692, 2025). "Overexpression of global MXD3 (gMX) or hepatic Mxd3 (hMX) was associated with obesity-related NAFLD pathophysiology in gMX + Dox, and liver fibrosis and HCC in hMX + Dox." (PMID 34943942, 2021). "Our results demonstrate that global actions of Mxd3 are central to the initiation of obesity in the gMX zebrafish through their effects on adipogenesis and that MXD3 could serve as a therapeutic target for obesity-associated liver diseases." (PMID 34943942, 2021). "Overexpression of mxd3 caused somatic growth and obesity, which then deteriorated the systemic lipid metabolic dysfunction (Mxd3 modulated adipokines in the adipose tissue of gMX2), ultimately resulting in dyslipidemia, liver steatosis, and NASH in MXs+Dox-treated zebrafish." (PMID 34943942, 2021). "In our study, we found that MXD3 modulates adipokines in the adipose tissue of gMX2+Dox-treated zebrafish, and is accompanied primarily by obesity effects." (PMID 34943942, 2021). "Considering these data, the role of MXD3 in liver cancers is interesting, and its role in obesity and HCC is worth investigating." (PMID 34943942, 2021). "MXD3 expression is significantly upregulated in visceral adipose tissues in human obese adults as well as in a zebrafish model of diet‐induced obesity in which downregulation of MXD3 expression suppressed the formation of visceral adiposity." (PMID 32141244, 2020). "Recent studies have also demonstrated that prolonged MXD3 expression could increase lipogenesis and adipogenesis and have an effect on oxidative stress, which also drive lipid deposition and boost obesity in zebrafish." (PMID 34943942, 2021). "Thus, Mxd3 overexpression led to hyperplasia of adipose tissue in zebrafish, thereby involving an impact of Mxd3 on growth and obesity." (PMID 34943942, 2021). "In addition, we examined whether Mxd3 modulates adipokines in the adipose tissue of the gMX2 group and primarily accompanies obesity effects." (PMID 34943942, 2021). "To investigate whether overexpression of Mxd3 has a physiological effect on obesity, we inspected the appearance of fat tissues of gMX adults and revealed that they displayed a vivid “reply” to weight gain or obesity." (PMID 34943942, 2021). "Furthermore, to evaluate the probable roles of Mxd3 in the metabolism of gMXs or hMXs in further examinations on energy expenses that might influence obesity, we carried out the Alamar Blue metabolic assay in 6 dpf larvae." (PMID 34943942, 2021).
leukemia (3 papers, 2020 to 2025). A malignant (clonal) hematologic disorder, involving hematopoietic stem cells and characterized by the presence of primitive or atypical myeloid or lymphoid cells in the bone marrow and the blood. "Interestingly, we found that hypomethylation of MXD3 was positively associated with dysfunctional T cell phenotypes and shorter survival durations of the brain, melanoma, metastatic melanoma, leukemia, breast cancer, and KIRC cohorts." (PMID 34584637, 2021). "Intriguingly, our results demonstrated that hypomethylation of MXD3 mediated dysfunctional T-cell phenotypes and shorter life durations of brain cancer, melanoma, metastatic melanoma, leukemia, breast cancer, and kidney renal clear cell carcinoma (KIRC) cohorts." (PMID 34584637, 2021). "At the same time, analysis of gene-knockout phenotypes from genetic screens revealed that MXD3-knockout was a strong influencer of lymphocyte-mediated tumor killing in MC38 colon cancer (Kearney2018_NK_20) and K562 leukemia (Pech2019_NK_E:T = 2.5) models." (PMID 34584637, 2021).